LEPR (leptin receptor)
Diseases named in the same sentence as LEPR in open-access papers (continued):
Sharing a sentence is not in itself a finding about the gene and the disease.
Obesity (continued). "The female db/db models consisted of the deficient LepR with markedly elevated levels of leptin, insulin and leptin resistance, obesity and diabetes with levels of glucose around 500 mg/dL." (PMID 34063911, 2021). "Mutations within leptin or the leptin receptor cause early-onset obesity and hyperphagia, as described in human and animal models." (PMID 33922961, 2021). "In the case of the patient with severe obesity showing heterozygous LEPR variant p.F393S diabetes type 2, hypertension and metabolic syndrome were reported." (PMID 34448070, 2021). "db/db mice are an obesity model of lost function due to mutation in the gene encoding leptin receptor." (PMID 34630614, 2021). "Mutation of the leptin receptor (LepR), whereby a longer defective variant is expressed, causes hyperphagia, leading to obesity." (PMID 34831343, 2021). "The associations between the polymorphisms in LEP and LEPR genes and human obesity are still controversial." (PMID 34205732, 2021). "Pathogenic compound heterozygous variants of genes causing severe obesity are rarely reported, and most of them are located within the leptin receptor (LEPR) signaling cascade." (PMID 33922961, 2021). "To verify our findings on the negligible role of LCN13 in systemic metabolism, we additionally used the leptin receptor deficient db/db mouse, a genetic mouse model of obesity." (PMID 33536239, 2021). "The db/db mice are currently used as a mouse model of type 2 diabetes with a mutation in the gene encoding the leptin receptor, and they are susceptible to obesity and insulin resistance due to the deficiency of leptin." (PMID 34200167, 2021). "db/db mouse lacks leptin receptor which makes them susceptible to obesity, insulin resistance, and type 2 diabetic mellitus." (PMID 33986669, 2021). "ZDF rats are characterized by obesity, IR, and hyperlipidemia due to mutations in the extracellular region of the leptin receptor." (PMID 34366839, 2021). "Homozygous loss-of-function variants in LEPR also lead to severe early-onset obesity, hyperphagia, and hypogonadotropic hypogonadism." (PMID 34448070, 2021). "Leptin-deficient ob/ob mice and leptin receptor-deficient db/db mice are commonly used mice models mimicking the conditions of obesity and type 2 diabetes development." (PMID 34183063, 2021). "Multiple molecules and proteins are involved in the impairment of LepR signalling pathways, thus contributing to obesity-associated leptin resistance and hyperleptinaemia." (PMID 34208585, 2021). "In our study, we used mice with a homozygous mutation in the leptin receptor (LeptrDb−/−) which are hyperphagic and are considered a good model of obesity and diabetes induced by excessive calories intake." (PMID 34462492, 2021). "The monogenic murine models such as Lepob/ob and Leprdb/db mice result from a mutation in the leptin receptor gene, leading to hyperphagia, hyperglycemia, and extreme obesity, which more closely resembles the phenotype of type 1 diabetes." (PMID 34549996, 2021). "Among the PSGs, we found the LEPR (leptin receptor) gene which is known to be a key gene associated with obesity and diabetes." (PMID 34585119, 2021). "Our study aimed to evaluate the associations between the MC4R rs17782313, LEP rs7799039, and LEPR rs1137101 polymorphisms with obesity-related parameters in childhood and adulthood." (PMID 34205732, 2021). "BKS.Cg-Dock7m+/+Leprdb/Nju mice (BKS mice), which are deficient in leptin receptor expression, are characterized by obesity, insulin resistance, hyperglycemia, and dyslipidemia." (PMID 33588950, 2021). "Several studies relate leptin gene (LEP) and leptin receptor gene (LEPR) polymorphisms with obesity, insulin resistance and T2DM." (PMID 35052401, 2021). "Several studies have investigated the relationships between LEP G2548A/LEPR Q223R polymorphisms and obesity, diabetes, insulin resistance, dyslipidaemias and cancer." (PMID 34407095, 2021).
Obesity (continued). "Leptin deficiency and mutations in the leptin receptor are recognized rare causes of monogenic early onset, severe obesity, and recombinant leptin replacement therapy produces significant clinical benefit in these patients." (PMID 33777773, 2021). "The obesity of the Zucker (Crl:ZUC(ORL)-Leprfa) rats results from the leptin receptor mutation, which in consequence causes polyethiological obesity." (PMID 33833309, 2021). "Leptin deficient (ob/ob) and LepR deficient (db/db) mice, carrying mutations in leptin (ob) and LepR (db) genes, respectively, exhibit excessive eating, develop obesity and diabetes, and are widely used as animal models of T2DM." (PMID 34795562, 2021). "Consistently, vascular injury mouse models of obesity and diabetes have demonstrated that leptin deficiency or leptin receptor signaling defects protect against neointimal hyperplasia." (PMID 34064112, 2021). "We formally tested this idea using Zucker fatty fa/fa rats as an established genetic model of obesity, glucose intolerance, and fatty liver due to leptin receptor deficiency." (PMID 34064308, 2021). "The genetic contribution of obesity has been explored experimentally in the ob (mutation in the gene encoding leptin) and db (mutation in gene encoding leptin receptor) mouse models." (PMID 34777390, 2021). "Upregulated leptin receptor expression is associated with anthropometric and radiological measures of obesity among patients with EAC, and with advanced tumor and nodal stage." (PMID 33777773, 2021). "Loss of function of LEPR is associated with the elevated leptin levels and obesity, showing its participating in adipose biogenesis." (PMID 33807688, 2021). "Several studies have investigated the association of the LEP and LEPR genes with obesity, feed intake, growth and fat traits, and their cardio-metabolic implications in a variety of species." (PMID 34496773, 2021). "Leptin is an obesity-associated adipokine that is known to regulate energy metabolism and reproduction and to control appetite via the leptin receptor." (PMID 33799880, 2021). "In summary, the disease-causing variants in the LEPR gene found in the two patients interrupt the leptin-melanocortin signalling pathway and lead to severe early-onset obesity, pronounced hyperphagia, and permanent food-seeking behaviour." (PMID 33140236, 2020). "Pre-diabetes/diabetes from leptin receptor deficiency dominated obesity effects and these changes were greatest in females." (PMID 32374776, 2020). "Taking into consideration that obesity itself can cause oxidative stress, we found that the LEPR rs8179183 GG genotype specifically affects oxidative stress markers and alters leptin and adiponectin levels." (PMID 32517169, 2020). "Several attempts have been made to show a possible association between leptin and LepR polymorphisms and metabolic disturbances leading to obesity." (PMID 32069871, 2020). "Together, the highly significant changes in torsional biomechanical properties suggests leptin receptor deficiency and obesity had the largest functional changes in vertebral properties." (PMID 32374776, 2020). "In conclusion our study demonstrates that the LEPR Q223R SNP is associated with obesity measures in Sri Lankan populations and that the effects of the genotype vary according to the urban and rural areas of residence." (PMID 31948470, 2020). "Through the present study we aimed to replicate the association between the LEPR Q223R SNP with obesity related anthropometric measures and biochemical measures in a Sri Lankan population." (PMID 31948470, 2020). "The current study examined the effects of chronic OXT infusions on adipose tissue inflammation in a murine model of obesity and diabetes, the leptin receptor-deficient (db/db) mouse." (PMID 32819381, 2020). "In experimental studies, bilirubin can improve the insulin sensitivity in leptin receptor-deficient and diet-induced mice with obesity." (PMID 32698889, 2020).
Obesity (continued). "We investigated various body composition and white adipose features by comparing the response of C57BL/6J mice with HFD-induced obesity, leptin-deficient (ob/ob) mice and leptin receptor-deficient (db/db) mice to PNS treatment." (PMID 33042284, 2020). "Poor expression of LEPR in certain tissues was suggested to lead to leptin resistance, which is commonly associated with obesity." (PMID 31480192, 2020). "The study proved that the non-synonymous single nucleotide polymorphisms of the leptin receptor gene Q223R are a genetic factor responsible for the increased prevalence of obesity." (PMID 33114690, 2020). "The Zucker rat has defective leptin signaling due to a mutation in the leptin receptor which results in hyperphagic obesity, in which reduced lipid oxidation contributes to the obese state." (PMID 32326226, 2020). "The first LEPR mutation linked to severe obesity was described as a G to A transversion in the splice site of exon 16 (c.2597 +1G>A), which results in the exon 16 skipping and premature termination of protein synthesis." (PMID 32655492, 2020). "After diagnosis of monogenic obesity, e.g. LEPR deficiency, further diagnostic examinations to find the cause of obesity are dispensable." (PMID 33140236, 2020). "Obesity-causing LEPR mutations have also been linked to insulin resistance and development of T2DM, which due to its slow progression, often remains asymptomatic for many years." (PMID 32655492, 2020). "LEPR mutations, with consequent congenital leptin deficiency, also cause severe early-onset obesity, despite a normal birth weight." (PMID 33261141, 2020). "These mice display a mutation in the gene encoding the leptin receptor, and leptin deficiency confers susceptibility to obesity, insulin resistance, and T2DM." (PMID 32796637, 2020). "The results show that compound heterozygous variants in the LEPR gene are the cause for the severe early-onset obesity in both patients." (PMID 33140236, 2020). "Mice with leptin receptor deficiency exhibit polyphagia, resulting in severe obesity, elevated blood glucose, diabetes, and increased vertebral bone mass." (PMID 32374776, 2020). "The leptin receptor-deficient db/db mouse model is an accepted in vivo model to study obesity, type 2 diabetes, and diabetic kidney disease." (PMID 32899353, 2020). "In fact, all patients carrying an obesity-causing LEPR mutation (aged 4 to 55 years) show hyperinsulinemia to an extent consistent with the degree of obesity, but T2DM was only reported in two adults (41- and 55-year-old)." (PMID 32655492, 2020). "Mutations in the LEPR gene are associated with obesity in humans and fat deposition in animals such as cattle and pigs." (PMID 32703156, 2020). "Several studies further ascribe obesity-associated inflammation in the hypothalamus to alternations in leptin signaling at its cognate receptor (LepR)." (PMID 32152264, 2020). "Mutations in gene encoding leptin or the leptin receptor are reported to cause severe obesity, hyperphagia, and insulin resistance." (PMID 33113859, 2020). "LEPR has thus been considered a genetic marker associated with body composition, growth rate, and obesity in some pig breeds." (PMID 31480192, 2020). "Zucker- and ZDF-fatty rats are widely used as the respective animal models of obesity and diabetes caused by mutation of the leptin receptor." (PMID 32041091, 2020). "The first murine model, B6.BKS(D)‐Leprdb/J (db/db), has a monogenetic knockout mutation in the leptin receptor gene resulting in hyperphagia, marked obesity, and consequent hyperglycemia." (PMID 32382692, 2020). "For a more detailed summation, Lepob and LepR polymorphisms and their implications in obesity we would refer you to previously published excellent reviews on the subject." (PMID 32069871, 2020).
Obesity (continued). "Obesity due to deficient leptin receptor signaling in these ZDF rats was associated with significantly higher astrogliosis in the DVC but a marked reduction in density of GFAP-positive cells in the arcuate nucleus compared to wild-type control rats." (PMID 32152264, 2020). "The Q223R (rs1137101) single nucleotide polymorphism (SNP) of the leptin receptor (LEPR) gene has been associated with obesity measures in various ethnicities." (PMID 31948470, 2020). "As a case study, we investigated models associated with obesity due to Leptin receptor gene deficiency (ORPHA:179494)." (PMID 31986132, 2020). "We examined a well-characterized model of human obesity and type 2 diabetes, which carries the mutated leptin receptor (db) alleles." (PMID 32327974, 2020). "The investigation of the mediating effects of factors such as diet and exercise on the association between LEPR polymorphisms and obesity outcomes is warranted in future studies." (PMID 31948470, 2020). "Diabetic (db/db) mice develop obesity, insulin resistance, hyperglycaemia, and hyperlipidemia similar to that seen in human type 2 diabetes due to a spontaneous mutation in the leptin receptor gene." (PMID 32655412, 2020). "The current study examined the effects of chronic oxytocin infusions on adipose tissue inflammation in a murine model of obesity, the leptin receptor-deficient (db/db) mouse." (PMID 32819381, 2020). "Though the sample size was somewhat moderate in the present study positive associations between the LEPR Q223R polymorphism and obesity have been reported even in smaller study groups in other ethnic populations." (PMID 31948470, 2020). "This study explored the effects of changes in gut microbiota on normal or leptin receptor gene deficiency rats, and multi-angle analysis of the directivity of intestinal microbiota during the progression of obesity to T2DM." (PMID 32920548, 2020). "After fed by Purina #5008 for 3 weeks, up to 11 weeks old, Zucker leptin receptor gene-deficient rats (fa/fa) developed obesity and elevated blood glucose." (PMID 32817751, 2020). "Based on CoA contents, the obesity in Zucker rats cannot be clearly explained by functional deficiency in the leptin receptor alone." (PMID 32041091, 2020). "Research into the mechanisms and effects of obesity has relied on both diet- and genetically induced animal obesity models (e.g., leptin or leptin-receptor-deficient mice)." (PMID 32211204, 2020). "We found a SA-β-gal staining pattern in the cerebellum of 9 weeks old adult leptin receptor deficient ob/ob mice that was identical to the one observed in wild type mice, thus obesity-independent." (PMID 32634782, 2020). "We conducted a population based study to investigate the potential association between the LEPR Q223R SNP and obesity related measures in Sri Lankans." (PMID 31948470, 2020). "Mutations in the leptin or LepR gene result in severe, early onset obesity, both in animal models and in humans." (PMID 33396484, 2020). "These mice are leptin receptor deficient and represent a type II diabetes model characterized with obesity, hyperglycaemia and impaired wound healing." (PMID 32870741, 2020). "Several common polymorphisms of LEPR have been found, but only a few appear to have a major effect on obesity." (PMID 32517169, 2020). "MMP-2 was described as elevated at circulating level in obese humans, and furthermore, it has been implicated in leptin resistance causing IR and obesity in mice by leptin receptor cleavage." (PMID 32214011, 2020). "STZ selectively destroys pancreatic islets, leading to lack of insulin and hyperglycemia, whereas in db/db mice diabetes follows obesity and insulin resistance generated by a recessive mutation in the leptin receptor gene." (PMID 32666590, 2020). "Mutations of the LEPR gene are associated with monogenic forms of severe early onset obesity and hyperphagia." (PMID 31948470, 2020).
Obesity (continued). "In summary, our study has identified a novel frameshift LEPR mutation in severely early onset of obesity children belonging to consanguineous family from Indian subcontinent." (PMID 31070016, 2019). "Decreased hepatic MUP1 levels have been linked to obesity and type-2 diabetes in mice with either genetic (leptin receptor-deficient db/db) or dietary fat-induced obesity." (PMID 30782214, 2019). "The association of leptin and leptin receptor mutations with obesity has also been reported in humans." (PMID 31447640, 2019). "This work demonstrates identification of novel mutation in LEPR gene resulting into early onset of obesity." (PMID 31070016, 2019). "This is due to the fact that insulin resistance, obesity and hyperglycemia in these models are the result of a gene mutation (e.g., leptin receptor OB-r), which can rarely be observed in humans." (PMID 31771099, 2019). "Leptin and LEPR mutations are associated with early onset severe obesity, severe hyperphagia and some neuroendocrine abnormalities, such as hypogonadotropic hypogonadism, impaired growth hormone secretion and hypothalamic hypothyroidism." (PMID 30991789, 2019). "In Zucker diabetic fatty rats, a mutation in the leptin receptor, OB-R, is associated with leptin resistance and obesity." (PMID 30871282, 2019). "The knockdown of LepR specifically in endothelial cells of the BBB was functionally linked to impaired transport of leptin into the CSF and LepR positive brain regions, and aggravated obesity when mice were exposed to high fat diet." (PMID 30283080, 2019). "Zucker rats are significantly hyperphagic and quickly develop obesity (at around 4 weeks of age) due to a mutation in the leptin receptor (fa gene), like in human obesity." (PMID 31396298, 2019). "In this study, we found novel frameshift LEPR mutation in a consanguineous family with three children with hyperphagic early onset of obesity." (PMID 31070016, 2019). "In previous studies, occurrence of LEPR mutation in a cohort of 39 children of consanguineous origin was reported to be 3%, compared to the occurrence of LEPR mutation in four consanguineous families with severe obesity at 50%." (PMID 31070016, 2019). "While Zucker obese rats are a useful model of obesity, they represent a rare form of monogenic obesity (leptin receptor gene deficiency)." (PMID 31623375, 2019). "More specifically, the db/db mouse is a model of obesity-induced type 2 diabetes, because it demonstrates very high fat mass due to a mutation in its leptin receptor." (PMID 31323977, 2019). "Truncation of LEPR has been shown to cause morbid monogenic obesity and severe hyperphagia in mice (db/db) and humans." (PMID 30121879, 2018). "The WBKDF rat carries the fatty mutation (fa) in the leptin receptor gene, and homozygous animals (fa/fa) exhibit hyperphagia and obesity, in addition to insulin resistance and glucose intolerance." (PMID 29744365, 2018). "Polymorphisms in LEPR gene have been investigated in many association studies of obesity, T2DM and diabetes-related complications in recent years." (PMID 29301582, 2018). "Obesity in the Zucker rat is inherited as an autosomal recessive trait caused by a mutation in the leptin receptor gene." (PMID 29757972, 2018). "Traditionally, leptin-deficient (ob/ob) and leptin receptor-deficient (db/db) mice are used for studies on obesity but their utility in studying atherosclerosis is limited." (PMID 30914878, 2018). "On the other hand, leptin or LepR deficiency increases appetites, energy uptake, and leads to obesity in animal models and humans." (PMID 30551684, 2018). "The mutations identified to date in LEP and LEPR are ethnic-specific, and the prevalence of monogenic obesity caused by mutations within these two genes is as high as > 20% in Pakistani study populations with obesity." (PMID 30442103, 2018). "The current study highlights the implication of LEPR mutations in cases of severe early-onset obesity in consanguineous Pakistani families." (PMID 30442103, 2018).